GCG (glucagon)
Diseases named in the same sentence as GCG in open-access papers (continued):
Sharing a sentence is not in itself a finding about the gene and the disease.
Hyperglycemia (continued). "Modern studies have shown that berberine can reduce blood glucose in type 2 diabetic patients by increasing insulin receptor expression and increasing glucose efficacy or alleviate hyperglycemia by inhibiting the hepatic glucagon pathway in diabetic mice." (PMID 35399638, 2022). "GLP-1 protects against hyperglycemia by inhibiting glucagon secretion from pancreatic α cells, complementing its effect to stimulate insulin, and coordinating the islet hormones leading to lower blood glucose." (PMID 36077491, 2022). "Studies are also conflicting with regard to the contribution of glucagon‐induced stimulation of hepatic glucose output to the hyperglycemia of T1D." (PMID 35569125, 2022). "We found that SHBs expression induces hyperglycemia and glucose intolerance by enhancing glucagon-stimulated hepatic gluconeogenesis." (PMID 36394315, 2022). "As well as delaying the onset of hyperglycaemia, desHis1Pro4Glu9-glucagon, and particularly desHis1Pro4Glu9-glucagon(Lys12PAL), improved glucose handling and insulin action in addition to augmenting pancreatic insulin stores." (PMID 36005280, 2022). "Cross‐correlation analysis demonstrated a small in‐phase coordination between insulin and glucagon concentrations during fasting, which inverted during hyperglycemia." (PMID 35822422, 2022). "Further, GIP suppresses glucagon secretion in states of hyperglycemia while stimulating glucagon release in hypoglycemic situations." (PMID 35123462, 2022). "When performing the analysis for hyperglycemia similar results were produced for both cases (0.76 ± 0.03 vs. 0.76 ± 0.03, using glucagon and insulin respectively as templates—Panel b)." (PMID 35822422, 2022). "STZ damages pancreatic β-cells, which secrete insulin, thus inhibiting glucagon secretion and inducing hyperglycemia." (PMID 36104518, 2022). "Dual GIP and GLP-1 receptor co-activation enhances insulin secretion by 20–30% more than the single administration, improves insulin sensitivity, and reduces glucagon secretion, and the reduction in hyperglycemia additionally reduces the resistance to GIP." (PMID 36289848, 2022). "On the other hand, as the direct treatment of α cells with glucose increases the secretion of glucagon, the dogmatic in vivo inhibition of glucagon secretion in the presence of hyperglycemia seems to be an indirect mechanism." (PMID 36145148, 2022). "Two studies were identified during the full-text screening phase that selected glucagon doses that were defined as sub-anorectic or prevented hyperglycaemia." (PMID 36123404, 2022). "Sympathetic nervous system activation stimulates glucagon release, together with other anti-insulin hormones including cortisol and growth hormone, leading to hyperglycemia." (PMID 34055942, 2021). "Clinical, and experimental evidence has shown that T2DM occurs with elevated serum glucagon levels despite hyperglycaemia." (PMID 34502413, 2021). "(c) It potentiates glucose-dependent insulin secretion from the β-cells and inhibits glucagon secretion from the α-cells in the presence of hyperglycemia (increases insulin/glucagon ratio)." (PMID 33419065, 2021). "It appears that the oral or intragastric administration of Trp at supraphysiological levels stimulates glucagon secretion and hyperglycemia." (PMID 34444719, 2021). "The compounds possessed strong antagonist properties, dose-dependently reducing glucagon-mediated cAMP production and insulin secretion together with counteracting glucagon-mediated hyperglycaemia in vivo." (PMID 34093449, 2021). "Due to impaired insulin secretion and excessive glucagon secretion in T2DM patients, the glucagon/insulin ratio is abnormally increased, thus exacerbating the hyperglycemia." (PMID 34457002, 2021). "By blocking sodium-channel isoform NaY1.3 in pancreatic alpha cells, it inhibits glucagon release, thus reducing hyperglycemia and glycemic variability." (PMID 35005029, 2021).
Hyperglycemia (continued). "GLP-1 was first discovered as an incretin, which can prevent hyperglycemia by enhancing insulin secretion and inhibiting the secretion of glucagon." (PMID 34437383, 2021). "Pramlintide, an analogue of amylin, can be co-injected with insulin to delay gastric emptying and suppress glucagon secretion and has been demonstrated to improve post-prandial hyperglycemia in T1D." (PMID 37745178, 2021). "GLP-1 suppresses glucagon secretion from pancreatic a-cells only during states of hyperglycemia and euglycemia which reduces hepatic glucose production." (PMID 34577569, 2021). "Nevertheless, low levels of glucagon persist, suggesting that hyperglycemia possesses greater metabolic influence on α-cells." (PMID 34115756, 2021). "We confirm that activation of A1/C1 neurons evokes hyperglycemia, but by promoting glucagon release." (PMID 34787082, 2021). "The suppression of glucagon levels was attenuated during hyperglycaemia (median ΔAUC −63.4% vs −73.0%; p = 0.010) and overall levels were non-significantly higher (p = 0.085) in HI vs LO." (PMID 33241460, 2021). "Based on evidence for the contribution of hyperglucagonemia to hyperglycaemia in T2D, research demonstrated the use of glucagon antagonism to improve glycaemic control." (PMID 34566894, 2021). "This produces strong membrane depolarization and action potential firing, and–through the activity of VGSCs–prevents glucagon secretion during hyperglycemia." (PMID 35002748, 2021). "Under stress and injuries, this hyperglycemia directly results from raised blood catecholamine levels or increasing glucagon secretion and inhibiting insulin secretion indirectly." (PMID 35095738, 2021). "During hyperglycemia when β-cells are active, paracrine β-cell factors can be envisaged to contribute to inhibition of glucagon secretion." (PMID 32156704, 2020). "It has been reported that three quarters of islet were composed of α cells, and the level of circulating glucagon can be markedly elevated despite hyperglycemia." (PMID 33250773, 2020). "This so-called “stress hyperglycemia” results from the release of counter-regulatory hormones (glucagon, cortisol, and epinephrine), which oppose the action of insulin." (PMID 33297385, 2020). "We also show that overnight CR normalizes stress-induced hyperglycemia, while significantly decreasing insulin and glucagon production and increasing corticosterone and ketone body production." (PMID 33510613, 2020). "Glucagon, for example, is a catabolic hormone that functions as a potent gluconeogenic agent acutely inducing hyperglycaemia, yet prolonged treatment with glucagon in DIO mice can result in glycaemic benefit." (PMID 32140744, 2020). "On the other hand, studies in rats have suggested that quetiapine-induced hyperglycemia was produced by increased levels of glucagon and suppressed glucagon-like peptide-1 (GLP-1) more than insulin resistance." (PMID 32373066, 2020). "To understand the inadequately high glucagon levels that contribute to hyperglycemia in type-2 diabetes (T2D), we analyzed granule behavior, exocytosis and membrane excitability in α-cells of 68 non-diabetic and 21 T2D human donors." (PMID 32312960, 2020). "The unexpected V-shaped glucose response of dispersed α-cells indicates that intrinsic regulation cannot explain the physiological inhibition of glucagon secretion in hyperglycemia." (PMID 32312960, 2020). "Withholding early-PN has shown to reduce the degree of hyperglycemia, to lower the insulin requirements to prevent hyperglycemia, and to lower the insulin/glucagon ratio." (PMID 32867803, 2020). "An animal model, where this drug (2.5, 5, 10 mg/kg) was applied intravenously to Wistar rats, showed an acute increase in corticosterone and glucagon levels, which explains the establishment of hyperglycemia." (PMID 32373066, 2020).
Hyperglycemia (continued). "It has also been shown that exogenous glucagon or stimulation of alpha cells during hyperglycaemia stimulates insulin secretion, an effect that is dependent on both glucagon and GLP-1-receptors on the beta cell." (PMID 32894317, 2020). "T2DM patients are often detected with enduring fasting hyperglucagonemia, as well as insufficient postprandial suppression of glucagon levels, suggesting glucagon as an important contributor to the hyperglycemia of T2DM." (PMID 33250773, 2020). "We examined blood glucagon levels in RIP-CreΔLEPR-LEP, however, i.c.v. leptin injection lowered blood glucagon in insulin-deficient RIP-CreΔLEPR mice, while RIP-CreΔLEPR-LEP still showed hyperglycemia." (PMID 33071988, 2020). "An abnormally elevated glucagon level and increased hepatic glucagon sensitivity are the primary reasons for hyperglycemia in type 2 diabetic patients." (PMID 31976031, 2020). "We report here that liraglutide ameliorates hyperglycemia in mice with type 1 diabetes by inducing insulin+glucagon+ cells and insulin-producing cells from the pancreatic ducts." (PMID 32477262, 2020). "Differences in glycemic control between the two groups were mainly observed in postprandial BG, suggesting that DU's mechanism of insulin secretion and glucagon suppression during hyperglycemia contributed to the lowering of postprandial BG." (PMID 31168938, 2020). "Plasma glucagon levels are constantly elevated in T2D patients and contribute to hyperglycemia by stimulating hepatic gluconeogenesis." (PMID 33379327, 2020). "Previously, we suggested that amylase has possible regulatory effects only on postprandial hyperglycemia and on insulin/glucagon release, as in previous studies by our lab, we showed that the mode of amylase infusion did not affect basal glucose levels." (PMID 33294459, 2020). "Mice lacking fumarase (Fh1) in their β cells (Fh1βKO mice) develop progressive hyperglycemia and dysregulated glucagon secretion similar to that seen in diabetic patients (too much at high glucose and too little at low glucose)." (PMID 30415925, 2019). "After surgery, indices of IS improved, GIP and glucagon levels decreased significantly in both the groups, while there was no significant change in indices of β-cell function in those with hyperglycaemia." (PMID 30948746, 2019). "Infections can induce hyperglycemia by increasing the secretion of glucagon, catecholamines, and cortisol." (PMID 31114536, 2019). "It is shown how the receptor internalization results in tolerance of the blood glucose concentration to glucagon-induced hyperglycemia." (PMID 31571122, 2019). "As alluded to above, it is poorly understood how glucagon secretion is suppressed during hyperglycemia." (PMID 31284506, 2019). "The insulin secretion response to glucose was attenuated in the hypoglycemic range and it was expected that the decrease in glucagon due to GLP-1 seen in hyperglycemia would disappear." (PMID 31781045, 2019). "Post-transplant DM is due to an impaired β-cell function and glucose-induced glucagon suppression during hyperglycemia, which can be reversed by GLP-1R." (PMID 31261624, 2019). "Knockdown of p52 lowers glucagon-stimulated hyperglycemia, while p52 overexpression augments glucagon response." (PMID 31541100, 2019). "Mechanisms to reduce circulating glucagon levels and antagonize the hepatic glucagon response in target tissues are well-recognized means to reducing hyperglycemia in diabetes." (PMID 31541100, 2019). "In pancreatic α cell-specific IR knockout mice, increased postprandial plasma glucagon levels and hyperglycemia have been observed." (PMID 31357734, 2019). "report that hyperglycemia impairs glucagon secretion by SGLT-dependent elevation of intracellular Na+, leading to acidification, reduced ATP production, and dysregulated KATP channel activity in α cells." (PMID 30415925, 2019).
Hyperglycemia (continued). "The results showed that p52 liver-specific overexpression increased fasting blood glucose and augmented glucagon-stimulated hyperglycemia in mice." (PMID 31541100, 2019). "High-fat diet (HFD) fed mice exhibit impaired glucose tolerance and insulin resistance leading to hyperglycemia, hyperinsulinemia and dysregulated glucagon secretion." (PMID 30849121, 2019). "Type 2 diabetes (T2D) results from a combination of insufficient insulin secretion and defective glucagon secretion and culminates in hyperglycemia." (PMID 30415925, 2019). "In contrast, in T1DM patients glucagon concentrations remain partially elevated even after meals and most likely aggravate postprandial hyperglycemia." (PMID 31717811, 2019). "The consequences of increased glucagon during fasting and unsuppressed glucagon secretion in response to meals are an increased rate of hepatic glucose production contributing to hyperglycemia." (PMID 30849121, 2019). "Insulin reduces postprandial hyperglycemia by promoting glucose disposal to target tissues, while glucagon stimulates hepatic gluconeogenesis to maintain blood glucose levels during fasting or starvation." (PMID 31541100, 2019). "Dysregulation of the hepatic glucagon response induces excessive hepatic glucose production, contributing to fasting hyperglycemia in diabetes." (PMID 31541100, 2019). "Firstly, NODAT was due to an impaired β-cell function and glucose-induced glucagon suppression during hyperglycemia." (PMID 31261624, 2019). "Tri-agonist analogues, which activate the glucagon, GLP-1 and GIP receptors, have been developed, with the aim that the additional GIP activity will further offer better protection from glucagon-induced hyperglycaemia." (PMID 29412829, 2018). "A similar effect is seen in individuals with T2D where elevated plasma glucagon levels contribute to hyperglycemia." (PMID 29558502, 2018). "On the other hand, suppression of glucagon secretion by hyperglycemia relies on paracrine regulation, including insulin-induced inhibition and/or somatostatin-induced inhibition of α-cells." (PMID 29416045, 2018). "The studies did show that glucagon suppression relative to hyperglycemia was impaired as is characteristic of type 2 diabetes, but that basal and stimulated levels were not different from normal controls." (PMID 30280274, 2018). "In animal studies, hyperglycaemia during cardiac arrest led to greater cerebral oxygenation, and blood glucose-increasing glucagon administration during cardiac arrest improved survival rate, cardiac function, and neurological outcome." (PMID 30005711, 2018). "The inappropriate increased α-cells portrays an increased α-cell function and concomitant secretion of glucagon, leading to hyperglycemia." (PMID 29449808, 2018). "Whereas GLP-1 decreases plasma glucose levels by exerting insulinotropic effects, glucagon stimulates hyperglycemia by enhancing hepatic glucose output." (PMID 30459715, 2018). "The second observation is that the acute hyperglycaemia from glucagon can be counter-balanced by GLP-1 co-administration." (PMID 30158899, 2018). "Typical phenotypes of growth retardation, persistent hyperglycemia, decreased number of insulin-producing β cells and increased number of glucagon-producing α cells were observed in the homozygous PAX4 KO rabbits." (PMID 29950431, 2018). "Sometimes, standard INH also causes hyperglycemia by blocking specific steps in Krebs cycle that requires nicotinamide adenine dinucleotide (NAD) and also from stimulating glucagon secretion." (PMID 28789699, 2017). "Excessive secretion of glucagon, a functional insulin antagonist, significantly contributes to hyperglycemia." (PMID 28775305, 2017). "The effect of these GLP-1 receptor agonists on postprandial hyperglycemia can be attributed mainly to suppression of glucagon secretion, reduced appetite, and slower gastric emptying." (PMID 28115994, 2017).
Hyperglycemia (continued). "Second, antagonism of SGLT-2, while promoting glucosuria, also stimulates glucagon secretion, contributing to hyperglycemia which can be significant in the volume-deplete patient." (PMID 29978156, 2017). "T2DM consists of an array of dysfunctions characterized by hyperglycemia, which results from insulin resistance, inadequate insulin secretion, and excessive glucagon secretion." (PMID 28521289, 2017). "This is consistent with previous findings that chronic hyperglycemia leads to a dramatic change in insulin to glucagon ratio and β-cell apoptosis in pancreatic islets." (PMID 28993702, 2017). "In type-2 diabetic (T2D) subjects, hyperglycemia is largely the consequence of insufficient insulin secretion and excessive glucagon secretion in a context of insulin resistance." (PMID 28887444, 2017). "Further evidence for a role of somatostatin in the regulation of glucagon secretion in hyperglycaemia is obtained from the kinetics of secretion." (PMID 27044660, 2016). "The relative contribution of dysregulated glucagon secretion and impairment of insulin secretion to hyperglycaemia in diabetic patients has been a matter of debate." (PMID 27053237, 2016). "Incretin, or hormone glucose-dependent insulinotropic peptide (GIP), is yet another critical hormone in glucose homeostasis and stimulates glucagon secretion and the eventual state of hyperglycemia." (PMID 27092078, 2016). "In hyperglycaemia paracrine factors become more important for glucose regulation of glucagon release, and the stimulated β-cells ultimately generate pulsatile secretion of the other islet hormones." (PMID 27044660, 2016). "Correlating positively with the development of hyperglycemia is an increase in the relative abundance of immunostainable glucagon-positive cells within the islets of mice bearing misfolded mutant proinsulin." (PMID 28702245, 2016). "It has been proposed to be a paracrine regulator of glucagon secretion with an important role for inhibiting glucagon secretion during hyperglycaemia." (PMID 27044683, 2016). "As Gcgr-/- mice exhibit resistance to STZ-induced hyperglycemia, we assessed the impact of glucagon signaling blockade on C57BL/6 mice made hyperglycemic with a single injection of either 175 or 225 mg/kg STZ." (PMID 27092792, 2016). "Pulsatile hormone release from human and mouse islets is generated by hyperglycaemia with coinciding pulses of insulin and somatostatin that are synchronized in opposite phase to the glucagon pulses." (PMID 27044660, 2016). "Even small changes in glucagon can greatly increase blood glucose; the addition of minimal doses of glucagon (0.50 ng/kg/min) is known to induce long-lasting hyperglycaemia." (PMID 27044683, 2016). "Somatostatin from the δ-cells is a potent inhibitor of both insulin and glucagon release and was early proposed as a paracrine regulator of glucagon release mediating the inhibitory effect of hyperglycaemia." (PMID 27044660, 2016). "In the islet α cells of STZ-induced diabetic mice with hyperglycemia, glucagon content and release was reported to increase due to enhanced Na+ current (INa), action potential duration and firing frequency." (PMID 27608006, 2016). "In the present study, DM mice model induced by HFD/STZ showed stable fasting hyperglycemia associated with impairment of glucose tolerance and elevation in FINS and glucagon, which indicated the glucose metabolism disorders." (PMID 27418937, 2016). "Insulin has traditionally been the focus of attention for diabetic research, but in recent years glucagon has received increased attention, as hyperglucagonemia contributes to the hyperglycemia present in T2D." (PMID 27136422, 2016). "T2D is a bihormonal disorder and hyperglycemia occurs as a result of inappropriate secretion of both insulin and glucagon." (PMID 27117413, 2016).